PEX11G (peroxisomal biogenesis factor 11 gamma)
Description:
Promotes membrane protrusion and elongation on the peroxisomal surface.
Synonyms: PEX11gamma; PEX11γ
Tractability: Antibody: UniProt predicts a signal peptide or a membrane-spanning region.
Gene: Protein-coding gene on chromosome 19 (7,476,869 to 7,497,449, reverse strand). Ensembl gene ENSG00000104883.
Subcellular location: Peroxisome membrane
Gene Ontology:
Molecular function: protein binding
Biological process: peroxisome fission; regulation of peroxisome size
Cellular component: peroxisomal membrane; peroxisome; protein-containing complex
Genetic constraint (gnomAD): Loss-of-function variants: 23 observed, 20.94 expected, observed/expected ratio (o/e) 1.1, 90% interval 0.79 to 1.55. The upper end of that interval is the gene's LOEUF score, 1.55, which puts it in group 6 of 6, group 1 being the genes least tolerant of losing a copy. Missense variants: 347 observed, 270.45 expected, observed/expected ratio (o/e) 1.28, 90% interval 1.17 to 1.4. Synonymous variants: 141 observed, 121.89 expected, observed/expected ratio (o/e) 1.16, 90% interval 1.01 to 1.33.
Gene-disease validity (ClinGen):
ClinGen rates the evidence that PEX11G causes each of these diseases.
peroxisome biogenesis disorder (autosomal recessive): No Known Disease Relationship.
Homologues: Orthologues: chimpanzee PEX11G (97% identical), macaque PEX11G (93% identical), guinea pig PEX11G (84% identical), pig PEX11G (81% identical), rat Pex11g (81% identical), dog PEX11G (80% identical), mouse Pex11g (78% identical), rabbit PEX11G (56% identical), zebrafish pex11g (52% identical), tropical clawed frog pex11g (50% identical), Drosophila melanogaster Pex11c (27% identical), Drosophila melanogaster CG33474 (24% identical), and 1 more.
Diseases named in the same sentence as PEX11G in open-access papers:
PEX11G is named in the same sentence as 2 diseases in open-access papers, as found by Europe PMC text mining. Sharing a sentence is not in itself a finding about the gene and the disease.
PEX11G shares sentences with these, for which no sentence is quoted: Breast Invasive Carcinoma (1 paper); cancer (1).